TRBV5-7 (T cell receptor beta variable 5-7 (non-functional))
Description:
Probable non-functional open reading frame (ORF) of V region of the variable domain of T cell receptor (TR) beta chain. Non-functional ORF generally cannot participate in the synthesis of a productive T cell receptor (TR) chain due to altered V-(D)-J or switch recombination and/or splicing site (at mRNA level) and/or conserved amino acid change (protein level). Alpha-beta T cell receptors are antigen specific receptors which are essential to the immune response and are present on the cell surface of T lymphocytes. Recognize peptide-major histocompatibility (MH) (pMH) complexes that are displayed by antigen presenting cells (APC), a prerequisite for efficient T cell adaptive immunity against pathogens. Binding of alpha-beta TR to pMH complex initiates TR-CD3 clustering on the cell surface and intracellular activation of LCK that phosphorylates the ITAM motifs of CD3G, CD3D, CD3E and CD247 enabling the recruitment of ZAP70. In turn ZAP70 phosphorylates LAT, which recruits numerous signaling molecules to form the LAT signalosome. The LAT signalosome propagates signal branching to three major signaling pathways, the calcium, the mitogen-activated protein kinase (MAPK) kinase and the nuclear factor NF-kappa-B (NF-kB) pathways, leading to the mobilization of transcription factors that are critical for gene expression and essential for T cell growth and differentiation. The T cell repertoire is generated in the thymus, by V-(D)-J rearrangement. This repertoire is then shaped by intrathymic selection events to generate a peripheral T cell pool of self-MH restricted, non-autoaggressive T cells. Post-thymic interaction of alpha-beta TR with the pMH complexes shapes TR structural and functional avidity.
Synonyms: TRBV57; TCRBV5S7; TCRBV5S7P
Gene: T-cell receptor variable (V) gene on chromosome 7 (142,520,090 to 142,520,556, forward strand). Ensembl gene ENSG00000211731.
Subcellular location: Cell membrane
Gene Ontology:
Biological process: cell surface receptor signaling pathway
Cellular component: plasma membrane
Homologues: Paralogues in human: TRBV5-5 (92% identical), TRBV5-6 (89% identical), TRBV5-4 (82% identical), TRBV5-3 (76% identical), TRBV5-1 (70% identical), TRBV9 (61% identical), TRBV13 (55% identical), TRBV7-6 (46% identical), TRBV7-7 (46% identical), TRBV11-3 (45% identical), TRBV7-9 (45% identical), TRBV11-2 (44% identical), and 39 more.